KRTAP22-1 (keratin associated protein 22-1)
Description:
In the hair cortex, hair keratin intermediate filaments are embedded in an interfilamentous matrix, consisting of hair keratin-associated proteins (KRTAP), which are essential for the formation of a rigid and resistant hair shaft through their extensive disulfide bond cross-linking with abundant cysteine residues of hair keratins. The matrix proteins include the high-sulfur and high-glycine-tyrosine keratins.
Synonyms: KAP22.1
Tractability: No criterion of Open Targets' tractability assessment is met for any kind of drug.
Gene: Protein-coding gene on chromosome 21 (30,601,087 to 30,601,382, forward strand). Ensembl gene ENSG00000186924.
Pathways (Reactome):
Developmental Biology: Keratinization
Gene Ontology:
Cellular component: cytosol
Genetic constraint (gnomAD): Loss-of-function variants: 1 observed, 1.46 expected, observed/expected ratio (o/e) 0.69, 90% interval 0.21 to 1.84. That is too few expected variants to judge how well the gene tolerates losing a copy. Missense variants: 48 observed, 59.02 expected, observed/expected ratio (o/e) 0.81, 90% interval 0.64 to 1.03. Synonymous variants: 19 observed, 23 expected, observed/expected ratio (o/e) 0.83, 90% interval 0.57 to 1.21.
Homologues: Orthologues: chimpanzee KRTAP22-1 (98% identical), pig KRTAP22-1 (67% identical), dog KRTAP22-1 (56% identical).